RNU6-269P (RNA, U6 small nuclear 269, pseudogene)
Gene: Small nuclear RNA gene on chromosome 16 (58,378,052 to 58,378,148, reverse strand). Ensembl gene ENSG00000212379.
Homologues: Orthologues: chimpanzee U6 (100% identical), macaque U6 (89% identical), rabbit U6 (68% identical), pig U6 (67% identical). Paralogues in human: RNU6-1145P (85% identical), RNU6-1075P (84% identical), RNU6-1316P (84% identical), RNU6-950P (84% identical), RNU6-140P (82% identical), RNU6-188P (82% identical), RNU6-25P (82% identical), RNU6-29P (82% identical), RNU6-378P (82% identical), RNU6-38P (82% identical), RNU6-41P (82% identical), RNU6-836P (82% identical), and 1288 more.